TNF (tumor necrosis factor)
Diseases named in the same sentence as TNF in open-access papers (continued):
Sharing a sentence is not in itself a finding about the gene and the disease.
dengue (continued). "In recent years, several studies have been published on anti-GFR tyrosine kinase inhibitors (TKIs) in dengue, such as dasatinib, sunitinib/erlotinib, gefitinib, brivanib, afatinib-derivative (L3), sunitinib/anti-TNF antibody, and TGF-β receptor 1 and 2 inhibitors (GW788388)." (PMID 36297236, 2022). "In our study, we observed that TNF-α levels were inversely correlated with platelet counts, which may suggest another link to the hemorrhagic features of dengue." (PMID 35631079, 2022). "Increased serum TNFα levels have been reported in patients with dengue." (PMID 36310878, 2022). "A study reported higher TNF-α levels in patients with severe illness in comparison to those with milder illness, which further proves the association of TNF-α in the development of severe dengue." (PMID 36423184, 2022). "In brief, TNF-α is a critical factor in the pathological process of severe dengue." (PMID 36423184, 2022). "Inflammatory cytokines IL-1β and TNF-α are commonly elevated in dengue cases." (PMID 36297236, 2022). "Expression of tumor necrosis factor alpha (TNF-α) and interleukin 8 (IL-8), among others, correlate with disease severity of dengue, and severe disease is associated with an excessive and long-lasting inflammatory response with inadequate response to anti-inflammatory cytokines." (PMID 36399460, 2022). "As in our previous studies, the dengue patients had high plasma levels of the cytokines TNF-α (p < 0.001), IL-6 (p = 0.005), IL-10 (p < 0.001) and, IL-18 (p = 0.001) and the chemokines CXCL8/IL-8 (p < 0.001), CCL2/MCP-1 (p < 0.001), CXCL10/IP-10 (p = 0.001) compared to healthy controls." (PMID 34578370, 2021). "Similar to the findings that a significant correlation between TBARS (MDA) and TNF-α levels was found in severe dengue cases, a positive correlation between TBARS (MDA) levels and proinflammatory cytokines, including L-1β and TNF-α, was observed in our patients." (PMID 34829738, 2021). "Interestingly, higher levels of NET components, IL-8, and TNF-α were found in patients diagnosed with the more severe dengue hemorrhagic fever compared to patients with dengue fever or healthy controls." (PMID 34073501, 2021). "In dengue fatalities, histopathology shows the virus triggered the pro-inflammatory cytokines TNFα along with IFNγ by mononuclear cell infiltration in liver, lung, and kidney, which is evidence for cytokine storm–induced pathogenesis in dengue." (PMID 34447698, 2021). "Our first priority was to compare the levels of IL-1b, IL-2, IL-4, IL-6, IL-8, IL-10, IL-12p70, IL-17A, IL-33, CD14, CD54, CD62E, CD62L, CD62p, CD106, CD121b, CD154, CD178, GM-CSF, IFN-g, MIF, ST2 and TNF in plasma samples of dengue group, OF group and Healthy group." (PMID 33809042, 2021). "Higher NS1 levels, which are associated with milder forms of dengue also correlated directly with high levels of IFN-γ from CD56+CD3+ NKT cells, TNF-α from CD16+ monocytes and IL-10 from granulocytes, suggesting a requirement for high viral antigen levels to achieve efficient innate cell activation." (PMID 34335578, 2021). "As IL-10 was found to be a key cytokine elevated during early illness during acute dengue, we compared the usefulness of IL-10 in predicting those who are likely to develop DHF, along with other key cytokines such as IL-6, TNFα and IL-1β, which cause vascular leak." (PMID 33199778, 2020). "Generally, TNF-α, as well as IL-4, IL-6, IL-8, and IL-10, are increased in dengue patients." (PMID 33072626, 2020). "Besides decreased percentages of CD24hiCD38hi transitional B cells/Bregs and CD27− naïve B cells in severe dengue infection, we also demonstrate here the inability of B cells isolated from dengue patients to produce IL-10 and TNF-α upon TLR/CD40 stimulation." (PMID 31736948, 2019). "However, the correlation between TNF-α production and the outcome of dengue disease is still uncertain." (PMID 31333657, 2019).
dengue (continued). "In dengue infection, platelet-monocyte aggregation was induced in dengue patients and the aggregate formation could enhanced the production of cytokines and chemokines by monocytes including TNF-α, IL-1b, IL-8, and CCL2/MCP-1." (PMID 30744623, 2019). "In humans with severe dengue TNFα levels have been found to be elevated." (PMID 31816907, 2019). "In this study, the multiplex bead array reported for the first time literature in human patients infected with dengue virus revealed that the GM-CSF, IFN-γ, IL-10, IL-15, IL-8, MCP-1, IL-6, MIP-1β, and TNF-α levels were significantly raised in dengue subjects compared to healthy controls." (PMID 30626045, 2019). "We determined CXCL10, IL-6 and TNFα levels in Dengue patients categorized into DF, DWS and SD." (PMID 30112159, 2018). "IL-1β is a known activator of endothelial cells and, along with monocyte-produced TNF, could contribute to vascular permeability in dengue disease." (PMID 30409217, 2018). "In a dengue hemorrhagic mouse model, skins obtained from hemorrhagic sites express higher levels of TNF transcripts and protein than that from non-hemorrhagic sites and TNF deficiency impedes DENV-induced hemorrhage development." (PMID 30409217, 2018). "Increased CXCL10 and TNFα levels in patients with Dengue as compared with healthy controls." (PMID 30112159, 2018). "TNF-α and IFN-γ are recognized as two of the most important factors associated to dengue progress." (PMID 28827898, 2017). "To investigate the relationships among endothelial glycocalyx, cytokine levels and disease severity in dengue, we conducted a prospective longitudinal study to measure serum HA, HS, IL-6, IL-10 and TNF-α concentrations in adults diagnosed with dengue and other acute febrile illness." (PMID 28393899, 2017). "In humans, dengue virus infection activates monocytes and the release of immunomodulatory cytokines, such as TNFα, from activated monocytes then contributes to increased permeability across endothelial cells and the hallmark vascular leak syndrome in more severe dengue cases." (PMID 28788062, 2017). "A paired comparison of these 15 cytokines (irrespective of the treatment group) showed that 12 (eotaxin, FGF-2, IFN-γ, IL-10, IL-1Ra, IL-1α, IL-8, IP-10, MCP-1, MDC, TNF-α and sCD40L) were differentially expressed between baseline and acute phase of dengue illness." (PMID 27459266, 2016). "In this study elevated TNF-α was observed in all dengue patients but higher in severe cases." (PMID 27301555, 2016). "In dengue, for example, monocytes from neonates treated in vitro with the virus when compared with monocytes from adults, produce significantly lower amounts of TNF-α and IL-6." (PMID 27560782, 2016). "Severe dengue has been proposed to be an outcome of exaggerated immune response and pathology resulting from the onslaught of inflammatory mediators such as IL-6, IL-8, IL-10 and TNF-α." (PMID 26982706, 2016). "The trend of IL-8 in dengue patients was similar to TNF-α in this study." (PMID 27301555, 2016). "Importance of TNFα in dengue disease severity has been illustrated in various mouse models." (PMID 27007501, 2016). "Dengue-infected monocytes could stimulate cytokines/chemokines production (e.g., TNF-α and IL-1β) which are known to activate endothelial cell." (PMID 25722892, 2015). "Conflicting information regarding the association of TNF-α, specifically, with severe dengue has been reported but cytokines produced by DENV-infected cells remain the leading suspects for inducing severe dengue." (PMID 25783751, 2015). "Furthermore, the role of TNF-α in dengue disease severity has been demonstrated whereby the administration of anti-TNFα blocking antibodies delayed the fatal outcome of DENV-infected AG129 mice." (PMID 24699622, 2014). "Elevated levels of TNF-α in severe dengue patients have been measured." (PMID 24699622, 2014). "We also observed down regulation of IL1α, which may point to the possible role of TNFα and IL1α in dengue pathogenesis." (PMID 24727912, 2014).
dengue (continued). "Thus, the aim of this study was to investigate the relationships between in vivo secreted levels of NS1 and innate immune response parameters (TLR4 expression and TNF-α/NO production) in infected dengue patients with different clinical outcomes." (PMID 25580138, 2014). "Furthermore, due to its interference with TNF-α cytotoxicity, CLQ would probably reduce the inflammatory symptoms, such as high fever and backache, associated with dengue." (PMID 23431254, 2013). "We found that severe dengue was associated with a reduction of total T cells and an elevation of IL-10 and TNFα, which was not, produced by NS3-specific T cells." (PMID 23209731, 2012). "TNF-α has been recognized as an important factor for the development of the severe dengue disease." (PMID 22666132, 2012). "The concentration of TNF-α ranged from 0 to 184 pg/ml in dengue patients." (PMID 20090849, 2010). "Additionally, the cytokine storm characteristic of severe dengue, marked by elevated interleukin 6, tumor necrosis factor-alpha, and NS1 antigen levels, induces myocardial inflammation, microvascular leakage, and interstitial edema, further compromising cardiac function." (PMID 40546620, 2025). "Furthermore, the identification of a subset of CD24/CD38-double-positive, CD27-negative B cells, which did not produce TNFα or IL-10 upon in vitro stimulation, was associated with severe dengue in a paediatric study from Cambodia." (PMID 39066252, 2024). "Although the reasons for headache, vomiting and hepatic tenderness in dengue is not clear, it could be due to the high circulating levels of cytokines such as IL-6, TNFα, IL-1β and mast cell products, which are known to be elevated in patients with acute dengue." (PMID 35648794, 2022). "Many of the studies have also indicated that the levels of pro-inflammatory cytokines are elevated in severe dengue patients, such as interleukin (IL)-6, IL-8, tumor necrosis factor (TNF)-α, and IL-1β, which may result in cytokine storm and increase the severity of dengue in patients." (PMID 36235496, 2022). "Therefore, in consideration of propofol's inhibition activity on TNF-α production, propofol treatment may be a considerable agent to prohibit dengue disease progression." (PMID 33869639, 2021). "Increased levels of TNFα have been reported in DF than control, indicating as a predictive factor for dengue severity (DHF/DSS)." (PMID 34447698, 2021). "Among them, three pathways, e.g., hallmark of heme metabolism, hallmark of tumor necrosis factor alpha (TNF-α) signaling, and cellular response to transforming growth factor-β stimulus, were found to be targeted by the microRNAs enriched in all categories of the dengue patients." (PMID 32934118, 2020). "Importantly, IL-1RA alleviated the damage produced by inflammatory factors, demonstrating that IL-1β may have an important role in the pathogenesis of the dengue disease in a TNF-α-independent manner." (PMID 31824450, 2019). "This could be the result of priming by the pro-inflammatory environment found during acute dengue virus infection, as TNFα and IL-8, cytokines known to prime neutrophils for ROS production, were also found elevated in dengue patients as previously reported and in our own study cohort." (PMID 30687301, 2018). "If TNFα and CXCL10 were used as predictive biomarkers of disease progression, these biomarkers may aid in early identification of patients who are at a higher risk of more severe forms of Dengue." (PMID 30112159, 2018). "However, a sensitivity analysis solely on the five studies that used WHO 1997 definition remained the non-significant association between TNF-α-308 G>A and the risk of severe dengue." (PMID 30300401, 2018). "Similarly cytokine storm associated with enhanced dengue disease was detected in DENV infected marmosets, which showed a significant increase in plasma TNF-α as early as 3 days post-infection and significantly increased IFN-γ at 3, 6, and 20 days post-infection." (PMID 30568659, 2018).
dengue (continued). "Furthermore, AST and ALT displayed negative associations with TNF in the network of the dengue mono-infection group." (PMID 26271921, 2015). "Similarly, TNF-α level was also increased in the sera of dengue patients." (PMID 26226614, 2015). "However, we found that while DENV-NS3 specific T cells of those with past mild/sub clinical dengue infection were more likely to produce only granzyme B, those who were hospitalized due to dengue were more likely to have DENV-NS3-specific T cells that produce TNFα and IFNγ or TNFα alone." (PMID 25875020, 2015). "The correlation between elevated systemic levels of TNF-α and dengue disease severity has been reported in a number of in vivo mouse model of severe dengue, among which four of them have used anti-TNFα antibody treatment to demonstrate a reduced mortality rate." (PMID 24699622, 2014). "Based upon these data all together, activation of TNF-α in particular, but possibly of the NF-κB pathway as a whole, may be involved in the mechanism of vascular leakage and transition into severe disease in patients with dengue." (PMID 18398488, 2008). "In a subsequent analysis comparing mild dengue with the combined DFWS/SD group, significantly higher exosomal levels of IL-1β, IL-5, IL-10, IL-12, IL-13, and TNF-α were observed in the DFWS/SD group (all p < 0.05)." (PMID 41993203, 2026). "Key cytokines such as interferon-gamma (IFN-γ), tumor necrosis factor (TNF)-α, and interleukin (IL)-10 are pivotal in the pathogenesis of dengue." (PMID 38910682, 2024). "As part of the host immune response, various cytokines, including interleukin (IL)-2, IL-6, tumor necrosis factor (TNF)-α, and interferon (IFN)-γ, contribute to severe dengue." (PMID 38306389, 2024). "It has been shown that T cells collected from children who developed subclinical secondary infection produced more TNF-α, IFN-γ, and IL-2 after stimulation with dengue antigens than those from children presenting symptomatic secondary DENV infection." (PMID 38003826, 2023). "We showed that IFN-α, IFN-γ, TNF-α, IL-6, MCP-1, IL-2, IL-4, and IL-10 production was higher in patients with dengue than in those with AFI." (PMID 38003826, 2023). "CD4+ and CD8+ T cells from dengue-infected patients stimulated with envelope and NS3 dengue antigens produce multifunctional T cells secreting IFN-γ, TNF-α, and IL-10." (PMID 38003826, 2023). "More specifically, pro-inflammatory cytokines TNF-α, IL-1β, IL-6, and anti-inflammatory cytokine IL-10 have been shown to be elicited in DHF patients, and in dengue two-hit mouse models." (PMID 37298220, 2023). "Several cytokines, including TNF-α, IL-6, IL-10 and IFN-γ, have been proposed as potential predictors of dengue severity." (PMID 36674524, 2023). "TNFα, IL6 and IL8 are known to alter the vascular permeability of capillaries, triggering cases of vascular leakage in dengue." (PMID 37162062, 2023). "Plasma levels of IL-1β, TNF-α and IFN-ɣ were increased in plasma from dengue patients in the present report." (PMID 36569864, 2022). "Another dengue live attenuated tetravalent vaccine (DLAV) was developed very recently and it showed a rapid increase of IFNg+TNF-α+-producing CD4+ T cells and then CD8+ T cells within 8–14 days after vaccination." (PMID 35215836, 2022). "The addition of TNF-α enhances ROS and RNS production and apoptosis in dengue-infected endothelial cells." (PMID 35864519, 2022). "Among them, a vast panel of increased cytokines and chemokines in severe dengue, such as IFN-γ, GM-CSF, IL-10, CCL4/MIP-1β, IL-1β, CXCL8/IL-8 TNF-α, CXCL10/IP-10, CCL2/MCP-1, and IL-18." (PMID 35631030, 2022). "The earlier studies included few markers of severe form of dengue like plasmacytoid and dendritic cells, cytokines like IFN gamma, TNF alpha, IL 6, IL 10, MIF; chemokines like CXCL 10; complements like C3a, C5a; proteases like tryptase and chymase." (PMID 36091089, 2022).
dengue (continued). "Our further analysis showed a strong correlation of the plasma Gal-9 levels with prominent mediators of cytokine storm (IL-6, TNF-α, MCP-1, IP-10, and MIP-1α) and CRP as reported in dengue fever." (PMID 33947753, 2021). "An earlier report also demonstrated synthesis of TNF-α, IL-6, and IL-10 from circulating B cells, monocytes, and mDC in PBMC of pediatric dengue patients; culture supernatants from these purified B cells activated allogeneic T cells." (PMID 34335578, 2021). "In our study, higher plasma levels of the proinflammatory cytokines TNF-α, IL-6 and IL-18, and the anti-inflammatory cytokine IL-10 and the chemokines CXCL8/IL-8, CCL2/MCP-1 and CXCL10/IP-10 were found in the dengue patients compared to the healthy controls." (PMID 34578370, 2021). "We also observed significantly greater numbers of dual-functional IL-10+TNF-α+ granulocytes and IFN-γ+TNF-α+CD56+CD3+ NKT cells in dengue patients than in febrile controls, although the percentages of the former were low." (PMID 34335578, 2021). "Early studies have shown that ADE of the dengue virus infection downregulates the production of IFN-β, IFN-γ, TNF-α and IL-12, and upregulates the production of IL-6 and IL-10." (PMID 32046249, 2020). "More recently, MT has been reported among dengue patients and levels of LPS were accompanied with progression of dengue disease as LPS has been found to act along with DENV in triggering IL-6, PAF, and TNF-α." (PMID 33014899, 2020). "Many different chemokines and cytokines have been shown to be elevated in severe dengue such as IFN-γ, GM-CSF, IL-10, MIP-1β, IL-1β, IL-8 TNFα, IP-10, MCP-1, and IL-18." (PMID 33194836, 2020). "TNF-α, MIP-1β, IL-8 and IP-10, which have been described for their significant roles in dengue pathogenesis, were also produced by imHC, and the other two hepatic cell lines (except that TNF-α secretion was not detectable in Huh-7)." (PMID 33216752, 2020). "IL-1β increases the vascular permeability, especially in concurrence with TNF-α and IFN-β in many severe dengue profiles." (PMID 33014899, 2020). "Similar to previous reports, the pro-inflammatory cytokines IL-1β, IFN-γ, TNF-α and MIF were increased in plasma samples from patients with dengue at the acute phase compared to samples obtained after recovery." (PMID 31068600, 2019). "The next step was to quantify the serum levels of IL-1β, IL-6, IL-18, IL-10, TNF-α and CRP, as indicators of the inflammatory status in the dengue patients." (PMID 30901375, 2019). "Circulating levels of TNFα (p≤0.001) and CXCL10 (p≤0.001) levels were increased in Dengue patients as compared with controls." (PMID 30112159, 2018). "We observed that TNFα and CXCL10 levels were raised in patients with Dengue as compared with healthy controls." (PMID 30112159, 2018). "Autopsy tissues from dengue patients showed elevated levels of IFN-γ and TNF expressing cells in livers, lungs and kidneys and DENV RNA was detected in Kupffer cells producing these two cytokines." (PMID 30409217, 2018). "Particularly, we observed that circulating levels of TNFα and CXCL10 differed between Dengue patients with severe as compared with mild disease." (PMID 30112159, 2018). "Patients with Dengue had raised levels of CXCL10 (P <0.001) and TNFα (P <0.001) as compared with healthy controls." (PMID 30112159, 2018). "We investigated the association of circulating levels of cytokines such as Interleukin (IL)-6, tumor necrosis factor (TNF)-alpha and CXCL-10 in Dengue patients with differing severity of disease." (PMID 30112159, 2018). "For example, studies have shown that tumor necrosis factor α (TNF-α), IL-8 and IL-10 levels are higher in patients with severe dengue versus mild dengue fever." (PMID 28644404, 2017). "This study is an attempt to build a mathematical model, to address the combined effect of cytokines and immune mediators S1P, IL-1β, TNF-α, PAF and IL-10, and determine the severity of dengue at an early stage." (PMID 28284213, 2017).